OR2T10 (olfactory receptor family 2 subfamily T member 10)
Description:
Odorant receptor.
Synonyms: OR1-64
Tractability: Small molecule: it belongs to a druggable protein family. Antibody: UniProt places it where antibodies can reach, with medium confidence; UniProt predicts a signal peptide or a membrane-spanning region; its Gene Ontology location is reachable by antibodies, with medium confidence.
Gene: Protein-coding gene on chromosome 1 (248,590,487 to 248,597,700, reverse strand). Ensembl gene ENSG00000184022.
Subcellular location: Cell membrane
Pathways (Reactome):
Sensory Perception: Expression and translocation of olfactory receptors
Gene Ontology:
Molecular function: olfactory receptor activity; G protein-coupled receptor activity
Biological process: detection of chemical stimulus involved in sensory perception of smell; G protein-coupled receptor signaling pathway
Cellular component: plasma membrane; membrane
Genetic constraint (gnomAD): Missense variants: 320 observed, 377.96 expected, observed/expected ratio (o/e) 0.85, 90% interval 0.77 to 0.93. Synonymous variants: 121 observed, 141.96 expected, observed/expected ratio (o/e) 0.85, 90% interval 0.74 to 0.99.
Homologues: Orthologues: macaque OR2T10 (93% identical). Paralogues in human: OR2T4 (71% identical), OR2T29 (71% identical), OR2T5 (70% identical), OR2T2 (62% identical), OR2T35 (62% identical), OR2T3 (61% identical), OR2T34 (60% identical), OR2T1 (59% identical), OR2T27 (57% identical), OR2T11 (57% identical), OR2T6 (54% identical), OR2M2 (52% identical), and 80 more.